RNU1-148P (RNA, U1 small nuclear 148, pseudogene)
Gene: Small nuclear RNA gene on chromosome 8 (24,076,997 to 24,077,158, reverse strand). Ensembl gene ENSG00000207201.
Homologues: Orthologues: chimpanzee U1 (100% identical), macaque U1 (87% identical), rabbit U1 (76% identical), pig U1 (75% identical), guinea pig U1 (73% identical), rat U1 (71% identical), mouse Gm23972 (67% identical). Paralogues in human: RNU1-1 (93% identical), RNU1-2 (93% identical), RNU1-27P (93% identical), RNU1-28P (93% identical), RNU1-3 (93% identical), RNU1-4 (93% identical), RNVU1-18 (93% identical), RNVU1-29 (93% identical), U1 (93% identical), RNU1-89P (92% identical), RNVU1-28 (92% identical), RNVU1-7 (92% identical), and 134 more.